IL1B (interleukin 1 beta)
Diseases named in the same sentence as IL1B in open-access papers (continued):
Sharing a sentence is not in itself a finding about the gene and the disease.
heart disease (35 papers, 2012 to 2025). "IL-1α, IL-1β, and IL-18 are the primary pro-inflammatory cytokines implicated in heart disease pathophysiology." (PMID 38256155, 2024). "Increased serum levels of IL-8 and IL-1β have been associated with both acute and chronic inflammation originated from diverse pathological conditions, including heart disease." (PMID 39588199, 2024). "IL-6 is a pleiotropic cytokine (downstream of IL-1β action) and is a powerful predictor of the severity of heart disease." (PMID 39063055, 2024). "A protective effect of the IL1B-31 TC genotype against cardiac disease severity has also been reported." (PMID 39119291, 2024). "As a result, IL-1β has become one of the most widely studied cytokines to determine if it is a viable therapeutic target for a variety of heart diseases." (PMID 38256155, 2024). "IL-1β is a potent inflammatory cytokine elevated in various forms of cardiac disease and studied in previous clinical trials." (PMID 39763850, 2024). "As we know that IL-1β is an important cytokine released by M1 macrophage, a clinical trial demonstrates that targeting on IL-1β by canakinumab can lower the incidence of AF recurrence after electrical cardioversion in the patients with heart diseases." (PMID 39372400, 2024). "Proinflammatory factors such as IL-1β antagonists or antibodies have shown promising results in early clinical trials for heart disease." (PMID 37047468, 2023). "NLR family pyrin domain‐containing 3 (NLRP3)/IL‐1β signaling axis has been demonstrated to mediate S100a8/a9‐induced myelopoiesis in heart disease." (PMID 38023700, 2023). "The use of proinflammatory factors such as IL-1β antagonists or antibodies has made positive progress in heart disease early clinical trials and researchers continue to explore more effective cytokine treatment methods." (PMID 37047468, 2023). "IL-1α and IL-1β are proinflammatory cytokines and their levels are correlated with the severity and pathogenesis of heart disease." (PMID 37047468, 2023). "IL-1β is a cytokine that plays a key role in inflammatory processes in cardiac disease, it increases significantly in the myocardium in response to an acute ischemic event; and in the context of cardiac repair has contradictory implications." (PMID 35896860, 2022). "The expressions of pyroptosis-related NLRP3, GSDMD, caspase-1, IL-1β, and IL-18 in these heart disease patients were elevated." (PMID 35647057, 2022). "Pro-inflammatory cytokines such as TNF-α, IL-1β and IL-6 and inflammatory mediators like NF-kB were considerably boosted during the cardiac disease and similar momentum was observed in the disease control group mice." (PMID 32762480, 2020). "This balanced response likely explains the observed protective effect of the IL1B −31 TC genotype against cardiac disease severity." (PMID 33193300, 2020). "Previous studies also suggest that either mRNA or protein levels of IL-18 are enhanced in heart disease and heart infarction, and that IL-18 or IL-1β play a significant role in myocardial injury." (PMID 32503314, 2020). "As proinflammatory/profibrotic mediators are also augmented in cardiac disease, the effect of a range of proteins, including Ang II, TGFβ1, IL-1β, IL-1α, TNFα, IL-6 and IL-6 in combination with the sIL-6R on Cx43 mRNA expression was examined in CFs." (PMID 31909243, 2020). "Among all members of the IL-1 family, IL-1β has been extensively studied for its role in memory responses of innate immunity, fibrosis, inflammation, and heart diseases." (PMID 31057540, 2019). "TLR2 activation has a key role in metabolic and cardiac diseases and its presence is required to trigger IL-1β production in different animal models." (PMID 27882934, 2016). "The inflammatory response caused by heart disease is not limited to the myocardial tissue, and a large number of pro-inflammatory factors including IL-6, TNF-α, IL-1β, and monocyte chemoattractant protein-1 (MCP-1) also reach the brain through blood circulation." (PMID 38327496, 2024).
heart disease (continued). "In addition, the NLRP3/Caspase-1/IL-1β pathway is present in the inflammatory response in heart disease." (PMID 39640484, 2024). "The significantly increased EVs in the plasma of patients with heart disease may carry IL-1β and TNF-α and other pro-inflammatory cytokines transmit “danger or inflammatory signals” to other organs or cells, especially cardiomyocyte-derived EVs." (PMID 38327496, 2024). "In the case of IL-1β rs1800587, comparison of BP patients carrying wild genotype (C/C) against those with polymorphic genotypes (C/T+T/T) demonstrated that the majority of patients with polymorphic genotypes were suffering heart disorders (P = 0.005)." (PMID 31001258, 2019). "Regardless of a viral, autoimmune, or chemotherapy-induced trigger, many inflammatory cardiac diseases converge on NLRP3 activation and the release of pro-inflammatory cytokines such as IL-1β and IL-18." (PMID 40940808, 2025). "In cardiac tissues, IL-17 induces the expression of diverse proinflammatory cytokines/chemokines and demonstrates strong synergic action with IL-1β and TNF-α to induce an inflammatory milieu that augments cardiac disease progression through different pathways." (PMID 40672362, 2025). "The results presented here show a gradual increase in IL-1β and CRP levels even in the ω-3G, confirming the presence of an inflammatory effect induced by heart disease and CHF as reported by previous studies." (PMID 34265016, 2021). "IL-1 comprises 2 distinct gene products (IL-1α and IL-1β) that have generally indistinguishable biological activities and play a significant role in the pathogenesis of heart disease." (PMID 31393855, 2019).
respiratory diseases (33 papers, 2012 to 2025). "NLRP3-induced inflammation and the release of IL-1β and IL-18 are linked to various respiratory diseases." (PMID 40218944, 2025). "It has been reported that disruption of the redox balance by CS leads to the production of proinflammatory cytokines, i.e., IL-1β, IL-6, IL-8, and TNFα in smokers, regulation of which is closely associated with the progression of respiratory diseases, such as COPD." (PMID 33660061, 2021). "The primary function of IL-1β is to trigger the inflammasome and promote resistance toward respiratory diseases; hence, precautions should be taken while employing IL-1 antagonistic therapies." (PMID 40136649, 2025). "A critical aspect of this study was the assessment of inflammatory cytokines, specifically IL-6 and IL-1β, which are well-established mediators of acute and chronic inflammation in respiratory diseases." (PMID 40218944, 2025). "IL-1β plays a critical role in the inflammatory response of respiratory diseases by promoting the release of other pro-inflammatory cytokines and mediators, thereby contributing to airway inflammation and tissue damage." (PMID 38999876, 2024). "The multifunctional inflammatory cytokine TNF-α, which is known for its capacity to stimulate the IL-1β and IL-6 release, emerges as a pivotal player in the pathogenesis of respiratory disorders within lung injury models." (PMID 39596850, 2024). "IL-1β is released following RV infection and contributes to pathogenesis of respiratory disease by recruitment of inflammatory cells and enhancing production of IL-8." (PMID 31703379, 2019). "Among them, representative respiratory diseases-related targets included IL-6, IL-10, IL-1β, TNF-α, interferon (IFN)-γ, epidermal growth factor (EGF) and its receptor (EGFR), TNF-α, transforming growth factor (TGF)-β1, etc." (PMID 31530860, 2019). "Proinflammatory cytokines, like TNF-α, IL-1β, and IL-6, by neutrophils are produced, which have close links with respiratory diseases." (PMID 29483931, 2018). "Increasing data suggest that azithromycin suppresses the production of inflammatory cytokines such as TNF-α, IL-1β, IL-6 and macrophage inflammatory protein 2 apart from the antibiotic effect not only in respiratory diseases but also in genital infections." (PMID 25174641, 2014). "Despite this, it is clear that early innate immune responses of airway epithelial cells constitute an important component of first line of defense against respiratory disease, and, compatible with our data, lung epithelial cells can secrete IL-1β and IL-18 to induce the inflammatory response." (PMID 30978238, 2019). "Pro-inflammatory cytokines, such as IL-1β, TNF-α, and IL-6, were quantified in the serum due to their crucial roles in initiating and sustaining inflammatory responses, particularly in respiratory disorders." (PMID 39596850, 2024). "IL-1β is a pro-inflammatory cytokine involved as an effector of the NLRP3 inflammasome and is known to increase the incidence of respiratory diseases induced by PM2.5." (PMID 34684415, 2021). "Experimental exposure of pigs to LPS following porcine respiratory coronavirus (PRCV) infection has led to more severe respiratory disease and increased TNF-α and IL-1β levels." (PMID 29157279, 2017). "This study confirms that the TCM compound MBFD significantly enhances average daily weight gain in calves, elevates serum immunoglobulin levels (IgG, IgM), and reduces both respiratory disease incidence and pro-inflammatory cytokine levels (IL-6, TNF-α, IL-1β)." (PMID 41234407, 2025). "In addition, IL-6, IL-1β, and TNF-α are proinflammatory cytokines that participate in many inflammatory responses of the lung, and studies have shown that the abnormal expression of IL-6, IL-1β, and TNF-α is related to the pathogenesis of respiratory diseases." (PMID 34135982, 2021). "Patients with respiratory disorders without CPA had also significantly higher values for IFN-γ, IL-1b, IL-6, IL-8, and TNF-α compared to healthy individuals." (PMID 30333797, 2018).
respiratory diseases (continued). "Levels of IL-1b, IL-6, IL-8, TNF-α, and IFN-γ were significantly higher in CPA patients compared to healthy individuals (p < 0.001 and p = 0.008, respectively), but not different than in patients with respiratory disorders without CPA." (PMID 30333797, 2018).
retinopathy (32 papers, 2012 to 2025). "The expression and clinical significance of tumor necrosis factor-α (INF-α) and interleukin 1-β (IL-1β) in retinal cells of patients with type 2 diabetes (T2DM) retinopathy were detected by flow cytometry." (PMID 35979044, 2022). "Serums TNF-α and IL-1β are significantly elevated in patients with T2DM retinopathy and gradually increase with disease progression." (PMID 35979044, 2022). "In retinopathy models, mRNA expression of the inflammatory cytokines IL-1β and TNFα, as well as Sema3a, increased significantly compared to controls." (PMID 29975739, 2018). "To decipher the mechanism whereby microglia elicits its pathogenic effects in BLE-induced retinopathy, we sought to identify the NLRP3 inflammasone and IL-1β that provoke retinal destruction in mice." (PMID 27831552, 2016). "Cytokines that mainly seem to play a role in the development of retinopathy in DM are the pro-inflammatory cytokines interleukin-1β (IL-1β), IL-6, and tumor necrosis factor (TNF)-α, as well as the chemokine IL-8 as these are elevated in vitreous samples from PDR patients." (PMID 36662891, 2023). "This study further supports our hypothesis that microglial NLRP3 inflammasome activation may be a mediator of IL-1β-related photoreceptor degeneration in light-induced retinopathy." (PMID 27831552, 2016). "In addition, IL-1β is the most studied IL-1 family member in retinopathy, such as DR." (PMID 34737754, 2021). "The oxygen‐induced retinopathy model of AMD has increased senescent markers (p16Ink4a, p21Cip1 and SA‐β‐gal) and SASP, including Vegf, Il1β, Il6, Tgfβ1, and Pai1." (PMID 39604117, 2025). "Following MCC950 therapy, we observed that NLRP3 and IL-1β expression were suppressed, and that in Ang II-infused animals, NLRP3 suppression reduced retinopathy and dysfunction." (PMID 38360728, 2024). "The degree of retinopathy was evaluated by staining retinal sections with hematoxylin and eosin, and the expression of CCN1, HIF-1α, VEGF, caspase-3, Bcl-2, IL-1β, and TNF-α protein was analyzed by Western blotting and immunohistochemistry." (PMID 35445044, 2022). "We further found an increased co-location of NLRP3, Iba-1, and IL-1β in fluorescence and a concomitant increased protein expression of NLRP3, caspase-1, and IL-1β in western blotting in chronic blue light-induced retinopathy." (PMID 27831552, 2016). "Interestingly, P2X7−/− mice were protected from the NaIO3-induced retinopathy and inflammatory NLRP3, IL-1β and IL-6 gene expression in the retina." (PMID 36671003, 2023). "Its beneficial effects on retinopathy were studied in diabetic rats where the intraocular injection of NAP reduced apoptotic cell death via MAPK/ERK pathways, reduced HIF and VEGF levels, and downregulated IL-1B." (PMID 33895966, 2021). "The proinflammatory cytokine IL-1β was increased by ~61% in response to the development of retinopathy (p < 0.01 versus nondiabetic mice without retinopathy)." (PMID 26949291, 2016). "Considering the very little quantity of the transcribed protein of NLRP3 inflammasone and IL-1β in RPE–choroid complex, here we supposed that microglia might make much more contributions to the BLE-induced retinopathy in mice." (PMID 27831552, 2016). "Therefore, the aim of our study was to investigate the effect of Cs-A on the retinopathy in a type 2 DM animal model and to elucidate its potential mechanism, specifically, to study the alternation of expression levels of HMGB-1, IL-1β and TNF-α in the retinal tissues." (PMID 32019593, 2020). "IL-1β concentrations are higher in the vitreous of patients with PDR compared to non-PDR and controls, indicating that there could be a minimal acute inflammatory activity present in the early stages of retinopathy, which progressively increases in the most advanced stages of the disease." (PMID 25276840, 2014).
peripheral neuropathy (21 papers, 2014 to 2025). A disorder affecting the peripheral nervous system. "Because NAC prevents NF-kB activation, it suppresses the production of cytokines, including TNFα, IL-1β, and IL-2, which are important for the inflammatory pathway and the development of peripheral neuropathy." (PMID 41440136, 2025). "In regard to DRG, peripheral neuropathy increased the expression of IL-1β in this structure, corroborating data from the literature." (PMID 37175503, 2023). "The peripheral neuropathy is reported to be associated with MCP-1 induction, IL-1β release, and high levels of IL-6." (PMID 35273508, 2022). "The currently available evidence shows that inflammatory cytokines, such as tumor necrosis factor alpha (TNF-α), interleukin-1 beta (IL-1β), and IL-6, which are secreted by immune cells contribute to the induction and progression of peripheral neuropathy." (PMID 32133063, 2019). "Recent studies have indicated that MAPK and NF-κB signaling contributed to PTX-induced peripheral neuropathy and increased expression of pro-inflammatory cytokines, such as IL-1β and TNF-α, within the DRG." (PMID 31024320, 2019). "For example, the blockage of specific IL-1β and TNFα attenuated peripheral neuropathy in several animal models." (PMID 29963257, 2018). "The expression of cytokines and chemokines is a prominent feature of neuroinflammation and elevated levels of certain cytokines, such as TNFα, IL-6, and IL-1β, have been demonstrated in patients with painful peripheral neuropathies, such as GBS and CIDP34–39." (PMID 28811623, 2017). "The key role of pro-inflammatory mediators in the development of CIPN has found important confirmations in preclinical studies that proved the efficacy of specific IL-1β and TNFα blockage in attenuating peripheral neuropathy in relevant animal models." (PMID 28423567, 2017). "Thus, we propose that spinal microglial cells are a major source of IL-1β during the early phase of peripheral neuropathy." (PMID 31281242, 2019). "Both the extracts of WS significantly reduced the signs of peripheral neuropathy accompanied by reduction in PTX-induced high levels of MCP-1, IL-1β, and IL-6." (PMID 35273508, 2022). "It has been shown that inflammatory cytokines such as IL-1β, IL-6, and TNF-α are involved in the progression of BTZ-induced peripheral neuropathy." (PMID 32733956, 2020). "First, a single injection of D-mannose creates transient but complete reversal of allodynia in an animal model of peripheral neuropathy mediated by TNF-α, IL-1β and NO actions." (PMID 24884664, 2014). "Peripheral neuropathy of the sciatic nerve increased TNF‐α, IL‐1β, IBA‐1, and CD11b." (PMID 37786517, 2023). "Secondly, blockade of IL-1R1 with intrathecal administration of the IL-1 receptor antagonist (IL-1ra) during the early phase of peripheral neuropathy increased the expression of both astrocyte P450c17 and GFAP in the spinal cord dorsal horn, and this increase was blocked by IL-1β administration." (PMID 31281242, 2019). "We observed that non-treated peripheral neuropathy increased the expression of IL-1β proinflammatory cytokines in the nerve and DRG, as well as decreasing the expression of the anti-inflammatory cytokines IL-4 and IL- 10 in the nerve, corroborating previous studies." (PMID 37175503, 2023). "Macrophage infiltration and IL-1β upregulation in the DRG following oxaliplatin administration were markedly inhibited by the bvPLA2 pre-treatment, suggesting that bvPLA2 may exert immunomodulatory actions to prevent oxaliplatin-induced peripheral neuropathy." (PMID 26797636, 2016).